TNF (tumor necrosis factor)
Diseases named in the same sentence as TNF in open-access papers (continued):
Sharing a sentence is not in itself a finding about the gene and the disease.
infection (continued). "Pulmonary and splenic cytokine expression (TNF-α, GM-CSF) remained suppressed, while IL-12/p40 increased in mice administered alcohol 6 or 24 h prior to infection." (PMID 31821337, 2019). "The effect of Celecoxib treatment on these pathways was evaluated and Celecoxib treatment reduced the upregulation of several critical cytokines including IL-1α and TNFα following infection." (PMID 31842327, 2019). "The adequate production of proinflammatory cytokines such as INF-γ, TNF-α, IL-1, IL-12, and IL-6 is essential for the control of infection by intracellular parasites." (PMID 31827186, 2019). "CXCL8 production increases during infections and in response to LPS and pro-inflammatory cytokines (TNF and IL-1)." (PMID 31188820, 2019). "As expected, infection upregulated the expression of several inflammation-related genes, including TNF-α, IFN-γ, IL-1β, galectin-3, TGFβ, and IL-10, compared to naïve controls." (PMID 31244833, 2019). "In cardiac cultures infected with T. cruzi, different cytokines and chemokines such as TNF-α, IL-1β, and iNOS are secreted in response of the infection." (PMID 31569452, 2019). "The anti-HSV response in the presence of TLR2/9 involved increased differentiation of TNF-α- and iNOS-producing DCs (Tip-DCs) and the activation of NK cells, which was accompanied by increased recruitment of the latter to the site of infection." (PMID 31114761, 2019). "While all the cytokine levels returned to basal levels in wild-type mice by 2 days post-infection, Foxo3a mice showed sustained expression of IL-1β, CXCl-1, and TNF-α up to 3 days." (PMID 31796819, 2019). "In contrast to TNF, mast cells have been shown to contribute to increased IL-6 levels at the infection site (peritoneum) at very early stages following CLP." (PMID 31212724, 2019). "IL-1 and TNF-α represent the archetypal pro-inflammatory cytokines that are rapidly released upon tissue injury or infection." (PMID 31370350, 2019). "Deficiency of IL-10 improved the anti-virus ability of the mice at the early phase of infection through increasing either pro-inflammatory cytokines’ (IL-2, IL-6, IL-12, TNF-α, IFN-α, IFN-γ) production or PCV2-specific antibodies." (PMID 31551984, 2019). "It is noteworthy that at early infection there was an enhanced induction of pro-inflammatory cytokine response of TNF-α and IFN-γ, which gradually reduced to basal levels with the surge of regulatory cytokines, IL-4, IL-10, and TGF-β in later infection." (PMID 31031744, 2019). "SV-HUC-1 models produced more TNFα upon infection, and N927 and VP1 strains were the most potent inducers of TNFα secretion." (PMID 31417529, 2019). "Nevertheless, the levels of IL-1β, IL-6, and TNF-α in the HAdV-7 group were higher than the HAdV-3 group post 3, 5, and 7 days of infection (p < 0.01)." (PMID 30626350, 2019). "TNF-α expression increased significantly upon infection with M.tb MOI 1 and MOI 5 or stimulation with PPD, PHA, and LPS in CD3+ T cells and in CD14+ cells compared to uninfected and no-PM control PBMC." (PMID 31731429, 2019). "CD4+ Th1 T-cell-produced IFN-γ and TNF-α can activate bystander resting macrophages and prevent their infection by MTB." (PMID 30625198, 2019). "In case of CL, the levels of IL4, IL8, INFγ, and MMP2 in skin biopsies and levels of TNFα, IL10, IL15, IL32γ, TGFβ, sCD26, sCD30, Cortisol, Prolactin, and SOD1 in serum, have been associated with infection and disease susceptibility." (PMID 30648003, 2019). "Ly6C+ macrophages produce the cytokine TNF in response to infection, which activates resident Ly6C− macrophages to secrete CXCL2 and promote migration of neutrophils." (PMID 31551993, 2019). "Here, we investigated the interactions between TNF-α as a marker of inflammation and parasite infection and coinfection in wild wood mice (Apodemus sylvaticus)." (PMID 31368489, 2019).
infection (continued). "The neutrophils and monocytes in the infiltrate allow enhanced interferon (IFN)-γ, IL-12, and tumor necrosis factor (TNF) production that are both necessary for control of infection and create the Legionnaires’ pneumonia." (PMID 31268152, 2019). "While TNF is required for host defense against mycobacteria, TNF also has detrimental effects and generates inflammation and tissue damage during infections, particularly in the liver." (PMID 30923339, 2019). "Listeria monocytogenes was reported to induce IFNβ expression, suppress the production of IFNγ and TNFα, thereby promoting infection." (PMID 30984149, 2019). "It has been reported that TNF-α level is directly related to the severity of histologic lung lesion or host cell apoptosis after infection." (PMID 31551774, 2019). "It was previously shown, that after the ingestion of dead or dying M. tb-infected apoptotic neutrophils at the infection site, a proinflammatory response is triggered and macrophages become activated, releasing TNF-α." (PMID 31888124, 2019). "CX3CL1 mRNA expression was also detected in the ipsilateral DRG of infected mice at the 30th day post-infection, and the i.t. injection of TNF-α or IL-1β in naïve animals induced CX3CL1 mRNA expression in the spinal cord and ipsilateral DRG." (PMID 31138231, 2019). "The number of TNF-α positive hepatocytes was significantly higher in the livers of Gal-3 KO mice compared to the group of infected WT mice, 36 and 72 h after infection." (PMID 30800112, 2019). "C5a stimulates mast cell degranulation, stimulates the release of tumor necrosis factor-α (TNF-α) and histamine, and recruits phagocytes to sites of infection and inflammation by increasing adhesion molecule expression on the surface of endothelial cells." (PMID 31510052, 2019). "During infection, elevated levels of cytokines like TNF-α lead to increased blood leptin concentrations, diminished appetite, and antagonized growth." (PMID 31394828, 2019). "In general increased TNFα levels are induced during inflammation or infection possibly perpetuating intestinal inflammation." (PMID 30995806, 2019). "MET enhanced the number of TB10.4-TET+ cells at local and systemic sites during infection, decreased inflammatory cytokine production, most notably TNF-α, and improved mitochondrial bioenergetics in these cells at D35 post-infection." (PMID 31825836, 2019). "Indeed, infection caused upregulation of IL-6, TNFα and IL-1β, typically associated with classical activation, as well as of arginase and IL-10, which is linked to regulatory macrophages and may have profound suppressive effects on both innate and adaptive responses." (PMID 29579113, 2018). "(b), (c), (d) Product levels of NO, IL-6, and TNF-α in RAW 264.7 cells responding to infection with each strain (MOI 100) was measured 24 h after infection." (PMID 30064361, 2018). "TNF-α is a contributing factor for the inflammatory response against the infection of intracellular pathogens." (PMID 30245924, 2018). "In the brain, trauma, infection, or the presence of endogenic abnormal protein aggregates, such as amyloid-β (Aβ) peptides in AD, can activate the secretion of TNF-α, primarily produced by glial cells." (PMID 29422938, 2018). "In that respect, it should be mentioned that the use of TNF-α+ antagonists in asymptomatic individuals can promote the reactivation of infection by Leishmania sp." (PMID 29543867, 2018). "The Th1 responses and regulation of the recruitment of Th1 immune cells to the site of infection are characterized by expression of key cytokines and chemokine such as TNFα, IL-12, IFNγ, IL-6, IL-10 and MCP-1 among others." (PMID 30413750, 2018). "Some interactions between peripheral infection and parity were noted for TNF (p = 0.054), IL-12 (p = 0.061), IL-2 (p = 0.003), IFN-γ (p = 0.025), IL-8 (p = 0.151), and IL-5 (p = 0.031)." (PMID 29743113, 2018).
infection (continued). "The infection of WT mice with C. rodentium led to an increased production of the innate cytokines IL-6, TNF-α, and CSF3 (also known as G-CSF), as well as the prototype Th1 cytokine IFN-γ, and the Th17 cytokine IL-17." (PMID 29922289, 2018). "Again, our results demonstrated an upregulation of Th1 (IFN-γ, TNF, and IL-6) cytokines due to infection, significantly for IFN-γ in both MIF-/- and WT groups, regardless of pregnancy (P < 0.05)." (PMID 29867817, 2018). "In fact, the kinetics of release of a pivotal cytokine like TNF-a in immune responses induced by cryptococcal cell envelope components will reflect on the course of the infection, its containment, and ultimately its elimination by phagocytes." (PMID 30154942, 2018). "In contrast, the proinflammatory mediators IL-6 and tumor necrosis factor (TNF) were both significantly increased in sera from Il27ra−/− versus wild-type mice 24 h after Cl13 infection." (PMID 29593047, 2018). "During infection, the innate immune cells liberate inflammatory cytokines such as IL-1ß, and TNF-α, which play an important role in the release of prostanoids." (PMID 29301269, 2018). "The role of TNF during parasites infection greatly depends on the strain of parasites, the state of infection, and the amount of induced TNF." (PMID 30519229, 2018). "During the first weeks of infection, the pro-inflammatory cytokines TNF-α and IL-6 are required for activation of inflammatory cells and for a subsequent efficient Th1 immune response against the parasite." (PMID 29755471, 2018). "TNF-α is another major pro-inflammatory cytokine that promotes the antiviral state in uninfected neighbouring cells and recruits lymphocytes to sites of infection." (PMID 30509265, 2018). "infection, due to its ability to regulate both innate and adaptive inflammatory responses, e.g. production of TNF." (PMID 30293531, 2018). "Since an interaction loop of gp91phox-ROS-NF-κB p65 was detected in the senescent macrophages during PAO1 infection, we assessed the production of ROS and the expression of inflammatory cytokines including IL-6, IL-10, and TNFα." (PMID 30050663, 2018). "TNFα induces pathology in IOE infection, and TNFα is a driver of necroptotic cell death, a form of programmed necrosis involving RIPK1, RIPK3, and the effector protein MLKL." (PMID 30080899, 2018). "Infection significantly increased TNF-α expression in intact and sham females compared with their counterpart males in the same condition, inducing a sex-associated pattern." (PMID 30515051, 2018). "In the liver on day 7 post-infection, the expression of iNOS, IL-1β, IL-6, IL-12 p40, TNF-α, IL-10, TGF-β, CCR2, CCL2, IFN-γ and IL-4 was significantly up-regulated, and the expression of Arg-1 was down-regulated in both of MRP14-KO mice and WT mice." (PMID 29902248, 2018). "TNF-α in the serum of Gas6−/− infected mice were significantly higher than WT, indicating a systemic reaction to the infection." (PMID 29967614, 2018). "The expression of IL-6 and TNF-α at initial stages of infection and IL-10 at longer stages was also detected in the serum of mice infected with S. aureus; however, in all these reports, a molecular mechanism was not described." (PMID 29434603, 2018). "The present study demonstrated that concentrations of pro-inflammatory cytokines IL-1β, TNF-α, Cox-2 all peaked at 8 weeks post-infection." (PMID 30273397, 2018). "Analyzing absolute concentrations of select cytokines, we found that levels of GM-CSF, IL-12, IL-2R, MIP-1α, RANTES, and TNFα were significantly higher in DENV-stimulated culture supernatants from subjects with subclinical versus symptomatic infections." (PMID 30557313, 2018). "Typically, TNF-α mediates systemic inflammation and is expressed in response to infection or tissue injury." (PMID 30008038, 2018). "During infection, pro-inflammatory cytokines such as interleukin 12, interferon gamma (IFNγ), and tumor necrosis factor alpha (TNFα) are essential for parasite killing." (PMID 29867974, 2018).
infection (continued). "The mRNA level of TNF-α, a well-documented cytokine associated with H5N1 influenza virus infection, was measured at various time points after infection." (PMID 29327729, 2018). "In vivo, infection of mice with PRN-deficient B. pertussis also resulted in increased serum levels of some cytokines, such as TNF-α, IL-8 G-CSF, and IL-1ß, compared to infection with PRN-producing B. pertussis." (PMID 30581436, 2018). "In this study, we found that TNF plays a crucial role in the maintenance of CD169+ cells early after infection with VSV." (PMID 29142134, 2018). "Addition of a lower amount of sera in the TNF biological assay identified a weaker CrmD neutralization activity in three of the five mice that succumbed to infection after CrmD immunization (1 μl dose)." (PMID 29724993, 2018). "All untreated animals had a cytokine storm characterized by a continuous increase in cytokines levels, in particular pro inflammatory IL6, TNFα, IFNα, from day 5 post infection (D5) to the time to death." (PMID 30275474, 2018). "To investigate lymphocyte activity after infection, we quantitatively determined the presence of IL-2, IFN-γ, TNF-α, IL-4, IL-5, IL-17A, IL-12p70, and IL-22 in mouse sera at day 3, 5, 7, and 9 post-infection; the sera of healthy mice were used as controls." (PMID 30564216, 2018). "A surge in the amount of TNF-α signifies clearance of infection as it is an antiviral cytokine which effect the viral clearance as well as limiting the tissue damage." (PMID 29891859, 2018). "These humanized mice consistently express high amounts of GM-CSF, tumor necrosis factor alpha (TNF-α), and IL-6 mRNA in the lungs after infection." (PMID 30453598, 2018). "RIF+NAC treatment also resulted in a significant decrease in the levels of TNF-α at both 8 days and 15 days (three-fold decrease) post-infection compared to untreated control category." (PMID 30258443, 2018). "The infection of R848-primed BMDMs with live E. coli resulted in a significantly increased production of IL-1β and TNF-α as compared with unprimed BMDMs." (PMID 29515583, 2018). "In cultured human fallopian tube epithelial cells, GC inoculated at various multiplicities of infection (MOI = 1, 10, or 100) all result in production of TNFα, which can cause apoptosis." (PMID 30524442, 2018). "At the same time, children who later developed a secondary acquired infection had higher plasma cytokine concentrations (i.e., IL-6, IL-8, and TNF-α)." (PMID 29536210, 2018). "Acute vascular hyperpermeability (AVH) occurs in response to exposure to any of the vascular permeabilizing factors (e.g., histamine, vascular endothelial growth factor (VEGF), tumor necrosis factor (TNF)-α) that are involved with inflammation and infection." (PMID 29419739, 2018). "On the other hand, IL-8 and TNFα have been reported to directly enhance the rate of productive infection in activated T cells." (PMID 29997630, 2018). "To test the role of TNF in neuroimmunopathology and astrocyte activation in this infection, we treated IL-10 KO mice with neutralizing anti-TNF antibody or isotype control antibody for 5 days (days 5–9 p.i.)." (PMID 29866139, 2018). "Secretion of IL-12, IL-2R, MIP-1α, RANTES, GM-CSF, and TNFα was significantly lower by PBMC from subjects with symptomatic infection." (PMID 30557313, 2018). "In contrast, only low expression levels of TNF-α and IL-6 were detected in the microglial cells 6 and 12 hours following infection with ZIKV." (PMID 30359409, 2018). "TNF-α is suggested to be a considerable immune mediator in inflammatory response which is initiated by infection and other factors." (PMID 30382864, 2018). "Treatment of cells with PGE2 prior to infection with S. Typhimurium or Y. enterocolitica did lead to an increase in IL-1β secretion and a decrease in TNF-α secretion." (PMID 30429830, 2018).
infection (continued). "Although not reaching statistical significance, average serum levels of TNF-α, KC/IL-8, G-CSF and IL-1β on day 3 post-infection where higher in BPSMΔprn- compared to BPSM-infected mice." (PMID 29559630, 2018). "Markers of inflammation, including neutrophil infiltration and proinflammatory cytokine production in the BALF, such as TNF-α, IL-1β and IL-6, were determined 24 h post-infection." (PMID 29875759, 2018). "We demonstrate here that the accumulation of macrophage and monocyte at the GI wall is associated with increased inflammatory cytokines IL-1β, IL-6, TNFα and INFγ-cytokines which signal recruitment of more inflammatory cells to sites of infection." (PMID 30249047, 2018). "Supernatants from PPD-B stimulated samples were also checked for IL-1β, IL-6, IL-10, IL-12, and TNF-α production over the course of infection using the MSD multiplex platform." (PMID 29343690, 2018). "Its overexpression in macrophages has been linked to a significant decrease in MyD88 protein expression, as well as a reduced production of inflammatory mediators such as NF-κB, TNF-α, and IL-6 in response to infection or LPS stimulation." (PMID 29988529, 2018). "Analyzing the inflammatory response in the lungs, we saw, as expected, an induction of pro- (IL-1β, TNF-α, KC, IL-6) and anti-inflammatory (IL-10) chemo- and cytokines following infection with S. pneumoniae." (PMID 29449834, 2018). "In response to inflammation, proinflammatory cytokines (IL-1β and TNF-α) are produced to control infections." (PMID 29849489, 2018). "Tissue‐resident macrophages reacting to these signs of infection or injury exhibit a proinflammatory anti‐microbial M1 phenotype and secrete factors, such as tumor necrosis factor‐alpha (TNFα), that mediate additional inflammatory events." (PMID 30426723, 2018). "Infection of BMDMs cells with Hh induced a sustained release of the pro-inflammatory cytokines IL-6 and TNFα in the supernatants as compared to unstimulated BMDM." (PMID 29636751, 2018). "The role of TNF/TNFR1 signaling in M. tuberculosis infection relates to its contribution in granuloma formation that is needed to control the infection." (PMID 29751683, 2018). "Here, we show that tumor necrosis factor is produced by CD11b+ Ly6C+ Ly6G+ cells following infection with VSV." (PMID 29142134, 2018). "Shortly after infection with VSV, the number of CD169+ cells in spleen tissue decreased in TNF-deficient mice compared to spleen tissue harvested from WT animals." (PMID 29142134, 2018). "Others have showed that in vitro infection of rat intestinal epithelial cells can trigger an inflammatory response characterized by Tumor Necrosis Factor alpha (TNFα) signaling via NF-κB." (PMID 30405608, 2018). "In infection, resident macrophages are able to phagocytose microorganisms and to secrete IL-1 and TNF-α." (PMID 30298072, 2018). "Similar observations were made at gene expression level; the infection of Mφs led to a significant increase in TNF-α, IL-1β, and IL-6 mRNA levels, and IL-6 mRNA level was further enhanced with IFN-γ addition (p < 0.01)." (PMID 29503646, 2018). "With E. histolytica, the macrophage polarization skewed towards the M1 phenotype, as shown by the significant increase in iNOS expression and multiple proinflammatory cytokines, such as TNF-α, IL-1 and IL-6, exerting immunoregulatory roles during infection." (PMID 29420539, 2018). "Anti-TNF biologics are thus expected to modulate the effector and the memory T-cell response during infections and vaccination (vide infra)." (PMID 30314507, 2018). "Tendency of higher levels of TNF-α were observed when the PTB-isolated strains infected the macrophages compared to the EPTB-isolated strains infected macrophages depending on the infection time point." (PMID 29515555, 2018). "In our infection experiments, a significant lesion was observed in both B6.WT and B6.TNF−/− mice from day 21 after infection." (PMID 29403488, 2018).